MYCBPAP (MYCBP associated protein)
Description:
Plays a crucial role in centrosome-nuclear envelope docking during spermiogenesis, a key step for anchoring the centrosome to the nucleus that is essential for proper sperm flagellum biogenesis. Also required for acrosome biogenesis, manchette organization, and spermatid head morphogenesis, contributing to the complete and functional assembly of the sperm flagellum.
Synonyms: AMAP-1; AMAP1; DKFZp434N1415
Tractability: Antibody: its Gene Ontology location is reachable by antibodies, with medium confidence.
Gene: Protein-coding gene on chromosome 17 (50,508,409 to 50,531,501, forward strand). Ensembl gene ENSG00000136449.
Subcellular location: Membrane; Cytoplasm, cytoskeleton, flagellum axoneme; Cell projection, cilium, flagellum; Cytoplasmic vesicle, secretory vesicle, acrosome; Cytoplasm (Isoform 2)
Subcellular location (Human Protein Atlas): Vesicles
Gene Ontology:
Molecular function: protein binding; phospholipid binding
Biological process: spermatogenesis; acrosome assembly; chemical synaptic transmission; endocytosis; flagellated sperm motility; sperm flagellum assembly
Cellular component: cytoplasm; axonemal central apparatus; clathrin vesicle coat; sperm flagellum; sperm midpiece; acrosomal vesicle; membrane; motile cilium; synapse
Genetic constraint (gnomAD): Loss-of-function variants: 60 observed, 107.78 expected, observed/expected ratio (o/e) 0.56, 90% interval 0.45 to 0.69. The upper end of that interval is the gene's LOEUF score, 0.69, which puts it in group 2 of 6, group 1 being the genes least tolerant of losing a copy. Missense variants: 1,050 observed, 1,198.9 expected, observed/expected ratio (o/e) 0.88, 90% interval 0.83 to 0.92. Synonymous variants: 399 observed, 451.78 expected, observed/expected ratio (o/e) 0.88, 90% interval 0.81 to 0.96.
Homologues: Orthologues: chimpanzee MYCBPAP (99% identical), macaque MYCBPAP (91% identical), dog MYCBPAP (76% identical), pig MYCBPAP (76% identical), mouse Mycbpap (70% identical), guinea pig MYCBPAP (69% identical), rabbit MYCBPAP (67% identical), rat Mycbpap (67% identical), tropical clawed frog mycbpap (38% identical), zebrafish mycbpap (26% identical), Drosophila melanogaster lqf (9% identical), Caenorhabditis elegans epn-1 (7% identical). Paralogues in human: EPN3 (12% identical), EPN1 (10% identical), EPN2 (9% identical), CLINT1 (9% identical), ENTHD1 (7% identical).
Diseases named in the same sentence as MYCBPAP in open-access papers:
MYCBPAP is named in the same sentence as 1 disease in open-access papers, as found by Europe PMC text mining. Sharing a sentence is not in itself a finding about the gene and the disease.
MYCBPAP shares sentences with these, for which no sentence is quoted: colorectal cancer (1 paper).